PWWP3B (PWWP domain containing 3B)
Synonyms: MUM1L1; FLJ33516
Tractability: PROTAC: ubiquitination databases record sites on it.
Gene: Protein-coding gene on chromosome X (106,168,304 to 106,208,963, forward strand). Ensembl gene ENSG00000157502.
Gene Ontology:
Cellular component: extracellular exosome
Homologues: Orthologues: chimpanzee PWWP3B (99% identical), macaque PWWP3B (94% identical), pig PWWP3B (78% identical), dog PWWP3B (77% identical), rabbit PWWP3B (75% identical), rat Pwwp3b (66% identical), mouse Pwwp3b (65% identical), guinea pig PWWP3B (65% identical), tropical clawed frog pwwp3a (33% identical), zebrafish si:dkey-57k2.7 (22% identical). Paralogues in human: PWWP3A (44% identical), PWWP4 (41% identical).
Diseases named in the same sentence as PWWP3B in open-access papers:
PWWP3B is named in the same sentence as 4 diseases in open-access papers, as found by Europe PMC text mining. Sharing a sentence is not in itself a finding about the gene and the disease. The quoted sentences say what the papers report.
infection (1 paper, 2023). The state of being infected such as from the introduction of a foreign agent such as serum, vaccine, antigenic substance or organism. "Genes encoding prostatic acid phosphatase (ACPP), MUM1 like 1 (MUM1L1, also known as PWWP3B) and von Willebrand factor A domain containing 5A (VWA5A) represent infection-associated genes whose expression is up-regulated in TashAT2/BoMac." (PMID 37276213, 2023).
PWWP3B also shares sentences with these, for which no sentence is quoted: cancer (3 papers); melanoma (2); metastatic tumors (1).